DND1 (DND microRNA-mediated repression inhibitor 1)
Diseases named in the same sentence as DND1 in open-access papers (continued):
Sharing a sentence is not in itself a finding about the gene and the disease.
breast carcinoma (6 papers, 2017 to 2024). "Conversely, DND1 protects BIM expression from miR-221 inhibition by competitive binding to BIM, thereby promoting apoptosis in breast cancer cells, but the expression level of DND1 is reduced in breast neoplasmss." (PMID 36052258, 2022). "When DND1 is knocked down in breast cancer cells, it promotes the decline of BIM mRNA due to the increased binding of miR-221 to the Bim-3’UTR, thereby inhibiting apoptosis or leading to a poor prognosis in breast cancer patients." (PMID 36052258, 2022). "The lowest DND1 levels were detected in a panel of human breast cancer cell lines with highest metastatic capability." (PMID 34359581, 2021). "We discuss below the studies on DND1 in breast cancer, gastrointestinal (GI) cancers, tongue squamous cell carcinoma (TSCC) and leukemia." (PMID 34359581, 2021). "We revealed that low Dnd1 level was a potential marker for breast cancer and that the expression level of Dnd1 was correlated with Bim, which is hall-marker of apoptosis." (PMID 28191469, 2017). "We further annotated the TCGA microarrays samples by taking into account gene expression levels of breast cancer and analyzed the expression correlation between Dnd1 and other genes." (PMID 28191469, 2017). "As the specific counteracting between Dnd1 and Bim, it is reasonable to assume that Dnd1 binds to Bim-3′UTR through counteracting miR-221 function in breast cancer." (PMID 28191469, 2017). "Although the expression of Dnd1 is necessary for germ-cell development, little is known about its function in other physiological conditions, like breast cancer development." (PMID 28191469, 2017). "An decreased mRNA level of Dnd1 was observed in breast cancer tissues with twofold lower than adjacent normal breast tissues." (PMID 28191469, 2017). "Here, the Dnd1 mRNA level was investigated in breast cancer tissues or cells and normal tissues or cells via qRT-PCR analysis." (PMID 28191469, 2017). "The results showed that Dnd1 expression level was lower in breast cancer cells or tissues and aberrant expression of the Dnd1 correlated with prognosis of patients with breast cancer." (PMID 28191469, 2017). "One such RBP, Dead end (Dnd1), is essential for regulating germ-cell viability and suppresses the germ-cell tumors development, yet how it exerts its functions in breast cancer has remained unresolved." (PMID 28191469, 2017). "Knockdown Dnd1 in breast cancer cells promotes Bim mRNA decay by competitive inhibiting the combination of miR-221 with Bim-3′UTR." (PMID 28191469, 2017). "In addition, DND1 expression was found to be positively correlated with the pro-apoptotic effector BIM expression in human breast cancer." (PMID 34359581, 2021). "Furthermore, comparison of 21 pairs of breast tumors and their neighboring mammary normal epithelial tissues found two-fold lower DND1 mRNA levels in breast cancer tissues compared to adjacent normal breast tissues." (PMID 34359581, 2021). "Overall, our results indicate that Dnd1 may modulate the proapoptotic properties of Bim and thus promotes the apoptosis in breast cancer cells." (PMID 28191469, 2017). "Together, we show that the RBP Dnd1 prohibits miRNA-dependent inhibition of Bim expression in breast cancer cells and underscores the tumor-inhibitory roles of the Dnd1 in breast cancer apoptosis, so it may be a possible therapeutic target of breast cancer." (PMID 28191469, 2017). "Our results pinpoint the mechanism by which Dnd1 exerts its function in breast cancer apoptosis." (PMID 28191469, 2017). "Finally, we provided evidences that Dnd1 protected the expression of Bim from repression of miR-221 by competitively binding to the of Bim, thus promoting the apoptosis of breast cancer." (PMID 28191469, 2017). "Nevertheless, the competitive binding between miR-221 and Dnd1 could give novel views into the modulation of Bim level, thus promoting the apoptosis in breast cancer cells." (PMID 28191469, 2017).
breast carcinoma (continued). "The KM Plotter tool was employed to assess whether Dnd1 mRNA level correlated with the survival of breast cancer patients." (PMID 28191469, 2017). "Here, we first survey the levels of Dnd1 and Bim in clinical breast cancer tissues and microarray, aiming to investigate whether the expression levels of Dnd1 and Bim are correlated with breast cancer development and whether the expression level of Dnd1 is positively correlated with Bim level." (PMID 28191469, 2017). "In addition, we focus on the effect of Dnd1 on breast cancer apoptosis in vitro." (PMID 28191469, 2017). "The new function of Dnd1 may contribute to a vital role in breast cancer development." (PMID 28191469, 2017). "However, limited information is available on the role of Dnd1 in breast cancer." (PMID 28191469, 2017). "However, the counteracting roles of Dnd1 with miRNAs in breast cancer development remain unclear." (PMID 28191469, 2017). "Hence, knockdown of Dnd1 decreases the apoptosis of breast cancer cells and defining Dnd1 as one of the key players that regulate breast cancer development provides the possibility of controlling the apoptosis of breast cancer cells by modulating the expression of the Dnd1 protein." (PMID 28191469, 2017). "Knockout of DND1 can reduce the expression of BIM and inhibit apoptosis of breast cancer cells." (PMID 38311675, 2024). "In breast cancer, patients exhibiting elevated levels of DND1 experience prolonged overall survival, and there exists a positive correlation between DND1 expression and the expression of the pro-apoptotic effector protein BIM in human breast cancer." (PMID 38311675, 2024). "DND1 might competitively interact with miR-221 against BIM and stabilized BIM mRNA, thus haploinsufficiency of DND1 assisted the breast cancer cells in escaping apoptosis via decreasing the expression of BIM." (PMID 34322380, 2021). "As Dnd1 was a conserved RBP which could bind to the AU-rich sites in mRNA 3′UTRs, we hypothesized that Dnd1 could also bind to Bim-3′UTR, thus enhancing the stability of Bim mRNA and promoting the apoptosis of breast cancer cells." (PMID 28191469, 2017). "The RNA binding protein DND1 is an evolutionarily conserved RBP that maintains the stability of BIM mRNA by binding to its 3’UTR and competitively inhibits the interaction between miR-221 and BIM, resulting in increased expression of BIM and promoting apoptosis in breast cancer cells." (PMID 36052258, 2022). "Finally, the mechanism of the interaction between Dnd1 and Bim is identified, in order to determine whether Dnd1 competitively bind to the Bim-3′UTR with miR-221, thus promoting breast cancer apoptosis." (PMID 28191469, 2017).
testicular teratoma (5 papers, 2018 to 2023). "In the current study, we newly generated Dnd1-Δ, a conventional knockout allele of Dnd1, and found that the Dnd1-Δ mutant mice showed defects similar to those of Ter mutant mice in spermatogenesis, oogenesis, and incidence of testicular teratomas, with a slight difference in spermiogenesis." (PMID 32339196, 2020). "We then examined embryonic lethality, spermatogenesis, oogenesis, and incidence of testicular teratoma for the Dnd1 mutant mice in these three mouse strains, especially focusing on the 129 strain, and found phenotypes similar to those of Ter mutant mice." (PMID 32339196, 2020). "We have also shown synergistic increase in testicular teratoma incidence in the male mice that were double mutants for Dnd1 and Nanos2 or Nanos3." (PMID 32339196, 2020). "In relation to testicular teratoma incidence, spermatogenesis, and oogenesis, the phenotypes of Dnd1-Δ mutant mice were similar to those of Ter mutant mice." (PMID 32339196, 2020). "Our results suggested that the expression of a cell cycle gene, Ccnd1, was upregulated by Dnd1 deficiency via the loss of Ezh2 expression and of H3K27me3 in Dnd1ter/ter testicular germ cells, and this molecular pathway may play a role in testicular teratoma development in Dnd1ter/ter testes." (PMID 29378702, 2018). "This association could be functionally relevant for the germline, as OCT4 expression is post-transcriptionally downregulated in the male germ cells where, analogous to LIN-41, DND1 maintains germline identity, preventing the onset of testicular teratomas." (PMID 37670562, 2023). "We have previously shown that both NANOS2 and NANOS3 interact with DND1 and that these complexes are essential for germ cell development, leading us to speculate that both NANOS2 and NANOS3 play a vital role with DND1 even in the regulation of testicular teratoma incidence." (PMID 32339196, 2020). "Therefore, the regulatory mechanisms of the DND1-NANOS3 complex in the case of testicular teratoma incidence are still unknown and may differ from those of NANOS2." (PMID 32339196, 2020). "We have previously shown that DND1 functions with NANOS2 or NANOS3 in both male embryonic germ cells and adult spermatogonia, which raises the question of whether DND1 also acts as a partner of NANOS family proteins to regulate the incidence of testicular teratoma." (PMID 32339196, 2020). "In addition, they showed that the incidence of testicular teratomas did not increase in the 129S1/SvImJ Dnd1+/KO heterozygous mutant male mice although Dnd1+/Ter male mice showed increased incidence in the same genetic background." (PMID 32339196, 2020).
hepatocellular carcinoma (3 papers, 2021 to 2025). A malignant tumor that arises from hepatocytes. "A piece of increasing evidence presents that DND1 acts as a wider function in human cancers such as primary acute myeloid leukemia (AML), colorectal cancer (CRC), and hepatocellular carcinoma." (PMID 34721738, 2021). "In hepatocellular carcinoma (HCC) cells, DND1 overexpression was found to inhibit spheroid formation, suppress HCC cancer cell stemness, inhibit epithelial-mesenchymal transition and increase the sensitivity of HCC cells to sorafenib." (PMID 34359581, 2021). "For instance, ectopic expression of Dnd1 promotes LATS2 mRNA decay through binding to the LATS2 3’-UTR, thus promoting YAP phosphorylation and inhibiting Epithel-to-Mesenchymal Transformation (EMT) in hepatocellular carcinoma (HCC)." (PMID 39890775, 2025).
tongue squamous cell carcinoma (3 papers, 2013 to 2024). A squamous cell carcinoma that arises from the tongue. "In tongue squamous cell carcinoma cells, DND1 has been identified as a target for miR-24." (PMID 38311675, 2024). "A recent study detected DND1 in human tongue squamous cell carcinoma (TSCC) and found that miR-24 directly targets DND1 mRNA." (PMID 23890083, 2013). "Similarly, the miR-24-mediated downregulation in DND1 expression level inhibited the expression of cyclin-dependent kinase inhibitor 1B (CDKN1B) and resulted in enhanced proliferation and reduced apoptosis in tongue squamous cell carcinoma (TSCC) cells." (PMID 34721738, 2021).
acute myeloid leukemia (2 papers, 2017 to 2021). Acute myeloid leukemia (AML) is a group of neoplasms arising from precursor cells committed to the myeloid cell-line differentiation. "On the other hand, Dnd1 expression is repressed in primary acute myeloid leukemia patients and inhibition of Dnd1 mRNA expression significantly attenuated NB4 differentiation." (PMID 28191469, 2017).
fertility disorders (2 papers, 2012 to 2019). "Despite the similarities in the rodent Dnd1 mutations, differences between the species mouse and rat were apparent in tumor incidence and severity of fertility disorders." (PMID 22655094, 2012). "Dnd1 is essential for formation and migration of primordial germ cells and its inactivation results in sterility in fish." (PMID 30999629, 2019).
liver cancer (2 papers, 2023 to 2024). An epithelial or non-epithelial malignant neoplasm that arises from the liver. "The Ter gene mutation (non-sense mutation of Dnd1) discovered in mouse teratoma studies have been investigated as a cause of human cancers and have been shown to have inhibitory effects on several cancers such as liver cancer and tongue cancer." (PMID 37127675, 2023). "In liver cancer cells, studies have revealed that the overexpression of DND1 can suppress the characteristics of liver cancer stem cells, impede spheroid formation, restrain epithelial-mesenchymal transformation, and enhance the sensitivity of liver cancer cells to sorafenib therapy." (PMID 38311675, 2024).
prostate carcinoma (2 papers, 2021). A carcinoma that arises from epithelial cells of the prostate gland. "Interestingly, while the majority of DND1 alteration is deletion or mutation in lung and prostate cancers, DND1 amplification prevails in kidney cancers." (PMID 34359581, 2021). "The results of this research show that DND1 is of great significance in the diagnosis and prognosis of patients with prostate cancer." (PMID 34721738, 2021). "Further research should be carried out to establish the relationship between miR-24, DND1, and P27 in prostate cancer." (PMID 34721738, 2021). "There is a strong expression of DND1 in the cytoplasm in poorly differentiated prostate cancer, while there is a moderate expression of DND1 in the cytoplasm in well-differentiated prostate cancer." (PMID 34721738, 2021). "The purpose of this paper is to explore the correlation between DND1 expression levels and clinical characteristics in prostate cancer (PCa) patients." (PMID 34721738, 2021). "Therefore, DND1 can be used as a good biomarker in the diagnosis and prognosis of patients with prostate cancer." (PMID 34721738, 2021). "Compared with paracancerous tissues, DND1 has a higher expression level in prostate cancer." (PMID 34721738, 2021). "However, no institution or individual has studied the expression level on the protein level and biological effects of DND1 in prostate cancer." (PMID 34721738, 2021). "Dead end 1 (DND1) plays a vital role during oncogenesis and cancer progression by regulating the mRNA content via competitive combination with miRNA, but what function it exerts in prostate cancer has been unclear." (PMID 34721738, 2021). "Furthermore, the overexpression of DND1 indicates a poor clinical prognosis in prostate cancer patients." (PMID 34721738, 2021). "And our study suggested that DND1 is overexpressed in prostate cancer." (PMID 34721738, 2021). "Our study provided evidence for the first time that DND1 could play a critical role in the progression of prostate cancer." (PMID 34721738, 2021). "Moreover, the underlying mechanism of an interesting phenomenon that there was strong DND1 expression in the luminal epithelium of most well-differentiated prostate cancer but there is almost no expression of DND1 in some poorly differentiated prostate cancer is still unclear." (PMID 34721738, 2021).
testis tumors (2 papers, 2008 to 2022). "DND1 deficiency results in male infertility and testis tumors due to the disruption of normal spermatogenesis." (PMID 36246621, 2022). "We previously found that inactivation of Dnd1 results in sterility as well as increased testicular tumors in the 129 mouse strain." (PMID 18509452, 2008). "Inactivation of Dnd1 results in sterility and testicular tumors." (PMID 18509452, 2008).
Azoospermia (1 paper, 2022). Absence of any measurable level of sperm,whereby spermatozoa cannot be observed even after centrifugation of the semen pellet. "In the current study, we identified a novel DND1 variant (E71A) causing azoospermia, similar to previous observations that P76L mutation resulted in the absence of germ cells in the small testes in mice." (PMID 36246621, 2022).
breast tumors (1 paper, 2017). "Most importantly, qRT-PCR assays were performed to detect the tissue distribution of Dnd1 and Bim transcripts in normalized pooled cDNA samples from 21 pairs of breast tumors with neighboring mammary normal epithelial tissues." (PMID 28191469, 2017). "An decreased expression level of Bim mRNA was observed in breast tumor tissues over normal tissues, and its expression was correlated with Dnd1 expression positively." (PMID 28191469, 2017). "Finally, the Dnd1 level was further analyzed in cDNA samples from 21 pairs of breast tumors and their neighboring mammary normal epithelial tissues." (PMID 28191469, 2017).
colorectal cancer (1 paper, 2021). A primary or metastatic malignant neoplasm that affects the colon or rectum. "However, one study contradicts this in that DND1 seems to play a tumor-promoting role in SW48 colorectal cancer cell line, as silencing DND1 suppressed cell proliferation and overexpression of DND1 reversed the tumor-suppressive effects of miR-24." (PMID 34359581, 2021).
embryonal carcinoma (1 paper, 2009). A non-seminomatous malignant germ cell tumor characterized by the presence of large germ cells with abundant cytoplasm resembling epithelial cells, geographic necrosis, high mitotic activity, and pseudoglandular and pseudopapillary structures formation. "Therefore, inactivation of Dnd1 expression is implicated as the causal event that drives PGCs to exit the germ line and transform to embryonal carcinoma cells and TGCTs in 129-Ter/Ter mice." (PMID 19440348, 2009).
gastric cancer (1 paper, 2021). A primary or metastatic malignant neoplasm involving the stomach. "And the expression of DND1 was significantly upregulated in gastric cancer cells, CRC cells, and TSCC cells." (PMID 34721738, 2021). "Recent studies have shown that microRNA-24-mediated suppression of DND1 suppressed the proliferation of gastric cancer cells and CRC cells." (PMID 34721738, 2021).
germ cell cancers (1 paper, 2021). "Additionally, emerging evidence indicates a role of DND1 not limited to only in germ cell cancers but also in some types of somatic cancers." (PMID 34359581, 2021).
glioma (1 paper, 2022). A benign or malignant brain and spinal cord tumor that arises from glial cells (astrocytes, oligodendrocytes, ependymal cells). "Consistent with this, high expression of the genes associated with PGC fate determination usually did not lead to poor outcomes of gliomas, such as KIT, DND1, NANOS3 and DDX4." (PMID 36435765, 2022).
intestinal polyposis (1 paper, 2013). "Finally, recent work suggests that susceptibility to both TGCTs and intestinal polyposis share genetic predisposition and that DND1 is normally expressed in the intestine." (PMID 23773267, 2013).
lymph node metastasis (1 paper, 2021). "Commonly, lymph node metastasis means the higher clinical stage, and in our study, the higher clinical stage is closely related to the expression level of DND1." (PMID 34721738, 2021). "We confirmed that high DND1 expression was significantly related to higher Gleason score, clinical stage, seminal vesicle invasion, and poor survival, but not with age, preoperative PSA level, and lymph node metastasis." (PMID 34721738, 2021).
male infertility (1 paper, 2022). The inability of the male to effect fertilization of an ovum after a specified period of unprotected intercourse. "Mutation in Dnd1 disrupted the interaction between DND1 and its partners, resulting in abnormal differentiation of male germ cells and male infertility in mice." (PMID 36246621, 2022).